EGFR (epidermal growth factor receptor)
Diseases named in the same sentence as EGFR in open-access papers (continued):
Sharing a sentence is not in itself a finding about the gene and the disease.
cardiac hypertrophy (continued). "Since Ang II advances renal hypertrophy in UNx mice and EGFR is involved in this process, this could be via EGFR inhibition." (PMID 40165104, 2025). "Knock-out experiments of the EGFR gene led to cardiac hypertrophy with fibrosis and inflammation." (PMID 37569355, 2023). "Similarly, we also detected increased CTGF and decreased EGFR in the tissue of the rat cardiac hypertrophy model by immunohistochemistry." (PMID 31200637, 2019). "In here, we have demonstrated the ERK1/2 signaling pathway cooperates with GPCR and EGFR signaling, and promotes the occurrence and development of cardiac hypertrophy by regulating the expression and binding states of CTGF and EGFR in the cell model induced by Ang-II stimulation." (PMID 31200637, 2019). "HB-EGF is then able to trans-activate EGFR and promote cardiac hypertrophy." (PMID 29221204, 2017). "EP4 may mediate the cardiac hypertrophy through EGFR/ERK1/2/Stat3 signaling, whereas PGE2-EP4 signaling may protect the heart from MI/R injury through cAMP/PKA or Stat3 pathway." (PMID 27190998, 2016). "The data indicate that EGFR activation may be a direct and independent inducer for cardiac hypertrophy." (PMID 26762600, 2016). "Our results suggested that the EGFR inhibition by either three small‐molecule inhibitors or shRNA silencing could attenuate cardiac hypertrophy in Ang II‐treated H9c2 cells and primary cardiomyocytes." (PMID 26762600, 2016). "The EGFR pathway activation has been shown to contribute to the development of cardiac hypertrophy." (PMID 26762600, 2016). "Previous studies suggest that epidermal growth factor receptor (EGFR) antagonism may be effective for the treatment of angiotensin II-induced cardiac hypertrophy and diabetic cardiomyopathy." (PMID 27087279, 2016). "Thus, compound 542 as well as AG1478 was chosen for the in vivo study to confirm the protective effect of EGFR inhibition on Ang II‐induced cardiac hypertrophy." (PMID 26762600, 2016). "In conclusion, the c‐Src‐dependent EGFR activation may play an important role in Ang II‐induced cardiac hypertrophy, and inhibition of EGFR by specific molecules may be an effective strategy for the treatment of Ang II‐associated cardiac diseases." (PMID 26762600, 2016). "ADAM10 is responsible for the proteolytic release of the ectodomains of numerous protein substrates, including specific ligands of EGFR (epidermal growth factor receptor) regulating the subsequent EGFR-dependent signal transduction pathways involved in cardiac hypertrophy." (PMID 24206753, 2013). "Expression of a dominant negative EGFR mutant in cardiomyocytes results in an increase in the left ventricular mass, consistent with cardiac hypertrophy, and a decrease in fractional shortening that could be normalized by cAMP stimulation." (PMID 24132149, 2013). "For example, HSP90 is a chaperone of both ErbB2 and EGFR and thus may be partially responsible for stability of these proteins in ErbB2 transgenic mice cardiac hypertrophy." (PMID 22912742, 2012). "EGFR is found in heart cells and EGFR signaling may be involved in myocardial hypertrophy." (PMID 20066142, 2009). "Multiple intracellular signaling pathways participate in cardiac hypertrophy, including PI3K/AKT, EGFR/MAPK and GP130/JAK/STAT3." (PMID 35855640, 2023). "Multiple intracellular signaling pathways participate in cardiac hypertrophy, including the IGF1R/PI3K/AKT, EGFR/MAPK, GP130/Jak/STAT3 and calcineurin/NFAT pathways." (PMID 35855640, 2023). "The stimulation of AT1R induced transactivation of epidermal growth factor receptor (EGFR) has been found to regulate the activation of extracellular signal-activated kinase (ERK) and cardiac hypertrophy in cultured cardiac myocytes." (PMID 36359731, 2022). "For example, Ang II-mediated cardiac hypertrophy is reported to occur via Src-dependent EGFR transactivation through AKT and ERK pathways that can be reversed with pharmacological inhibitors of EGFR." (PMID 34408653, 2021).
cardiac hypertrophy (continued). "Together, these results highlight a role for EGFR activation and subsequent signaling through ERK in the development of cardiac hypertrophy." (PMID 33923899, 2021). "Numerous intracellular signalling pathways participate in cardiac hypertrophy accompanied by increased protein synthesis, such as IGF1R/PI3K/AKT, EGFR/ MAPKs, gp130/Jak/STAT3 and calcineurin/NFAT." (PMID 32343488, 2020). "To explore the molecular mechanism by which LMP10 KO attenuates Ang II-induced cardiac hypertrophy, we examined a range of prohypertrophic signaling pathways, including IGF1R, gp130, EGFR, and calcineurin A, and their downstream mediators." (PMID 32581853, 2020). "The ERK1/2 cooperates with GPCR and EGFR signaling, and promotes the occurrence and development of cardiac hypertrophy by regulating the expression and binding states of CTGF and EGFR." (PMID 31200637, 2019). "Another important finding is that cardiac hypertrophy mediated by EGFR activation is Ang II‐independent, as demonstrated by the fact that EGF stimulation alone induced cardiac hypertrophy in H9c2 cells." (PMID 26762600, 2016). "In this regard, it was observed that Ang II did not induce cardiac hypertrophy and produced markedly less degree of apoptosis in transgenic mice with AT1R mutation lacking epidermal growth factor receptor transactivation." (PMID 36359731, 2022). "For example, GDF-15 promotes cardiac hypertrophy by protecting cardiomyocytes from apoptotic stimuli, but in constrast GDF-15 also seems to reduce myocardial hypertrophy by inhibiting the transactivation of EGFR." (PMID 35600479, 2022). "As EGFR/ErbB/HER receptors are known drivers of cell growth and proliferation via mitogenic signaling through Ras/Raf/MAP kinases, AKT and ERK1/2, they play key role in mediating cardiac hypertrophy." (PMID 34408653, 2021). "Our findings confirm the role of EGFR in AngII mediated cardiac hypertrophy, and highlight that EGFR is not involved in vivo in the damaging effects of aldosterone on cardiac function and remodelling." (PMID 22291909, 2012). "The results obtained in this study confirm the role of EGFR in AngII mediated cardiac hypertrophy, and highlight that EGFR is not involved in vivo in the damaging effects of aldosterone/salt on cardiac function and remodelling." (PMID 22291909, 2012). "In this study, we report that EGFR is not required for aldosterone/salt-induced cardiac hypertrophy and molecular remodelling." (PMID 22291909, 2012). "Compared with control mice, vascular ADAM17-deficient mice and ADAM17 antibody treated mice show alleviated cardiac hypertrophy, vascular medial hypertrophy, and perivascular fibrosis induced by Ang II via activating EGFR, which is independent of blood pressure regulation." (PMID 37521117, 2023). "There is evidence showing that vascular ADAM17-deficient mice and ADAM17 antibody treated mice have alleviated Ang II-induced cardiac hypertrophy, vascular medial hypertrophy, and perivascular fibrosis via activating EGFR, which is independent of blood pressure regulation." (PMID 37521117, 2023). "Though several studies demonstrated a role for EGFR-dependent signaling in cardiac hypertrophy and EGFR inhibitors attenuated organ deterioration, our findings indicate that systemic EGF and EGFR display no specificity for PH and RVH." (PMID 35053115, 2022).
liver fibrosis (61 papers, 2010 to 2026). "Consistently, pharmaceutical inhibition of EGFR is associated with amelioration of liver fibrosis in different murine models." (PMID 33520984, 2020). "Gene expression analysis indicated that EGFR signaling is associated with the progression of liver fibrosis." (PMID 28445529, 2017). "Although the mechanism underlying hepatic fibrosis is complex, the multi-functional transmembrane glycoprotein EGFR specifically interacts with EGF and TGF-β1, causing its dimerization and regulating cell growth, proliferation, and differentiation." (PMID 27342773, 2016). "Bmp-1 assumes a crucial function in this process by activating EGFR signalling in hepatocytes.Additionally, in fibrotic mice with a deficiency in Periostin, the reduction in liver fibrosis was counteracted by the introduction of exogenous Bmp-1, which coincided with the progression of EMT." (PMID 38216590, 2024). "Additionally, EGFR has strongly been associated with liver fibrosis." (PMID 34944593, 2021). "Collectively, our results suggest that PZH exerts pharmacological effects on liver fibrosis by modulating the EGFR/JAK1/STAT3 signaling pathway." (PMID 41181146, 2025). "Treg cell-derived AREG is stimulated to promote liver fibrosis by epidermal growth factor receptor (EGFR) activation." (PMID 40122853, 2025). "The findings reveal that PZH ameliorates liver fibrosis by inhibiting macrophage-mediated inflammation via blockade of the EGFR/JAK1/STAT3 signaling axis, providing a mechanistic foundation for its clinical application." (PMID 41181146, 2025). "Numerous studies revealed that the epidermal growth factor receptor (EGFR) is often expressed in the progression of hepatic fibrosis." (PMID 38560050, 2024). "Animal experiments also confirmed that EGFR was phosphorylated in the liver of MASLD mice, and inhibition of EGFR suppressed diet-induced hepatic lipid accumulation, OS, hepatic fibrosis and improved glucose tolerance in mice." (PMID 39604837, 2024). "We focused on the liver for the following reasons: (a) EGFR activation plays a detrimental role in the development of liver fibrosis." (PMID 38488009, 2024). "Previous report also showed the EGFR expression is involved in the emergence of CCl4-administered liver fibrosis occurs most likely through activating macrophages and hepatic stellate cells." (PMID 38560050, 2024). "This analysis unveiled several noteworthy findings, including the heightened activity of EGFR and VEGF signaling pathways in LSECs, as well as elevated TGFβ signaling in HSCs (the primary cell type associated with liver fibrosis)." (PMID 39691723, 2024). "Consistently, our study demonstrated that hepatocyte-derived CTGF increased the phosphorylation of p38 and p65 and promoted HSCs’ activation through EGFR, thereby contributing to liver fibrosis." (PMID 36232998, 2022). "Inhibiting EGFR reduces liver fibrosis and HSC activation in NAFLD based on recent research, indicating the dysregulation of EGFR in animal models of liver damage." (PMID 36297027, 2022). "As such, the inhibition of EGFR via TKIs such as erlotinib suppresses hepatic fibrosis, cirrhosis, and the development of HCCs." (PMID 34069911, 2021). "It was reported EGFR played the key role in CCl4-induced liver fibrosis, if the expression of EGFR was inhibited, fibrosis and stellate cell activation were attenuated." (PMID 34235224, 2021). "The CNV region Chr7:54813380-55274871 contains the gene encoding epidermal growth factor receptor (EGFR), a receptor tyrosine kinase expressed in activated hepatic stellate cells (HSCs) that is associated with the development of liver fibrosis." (PMID 33853536, 2021). "Several studies reported that EGFR/HER-2 inhibitors attenuated liver fibrosis through inhibition of HSCs29,30." (PMID 32901093, 2020). "In liver fibrosis, there were divergent proteome repertoires regarding EGFR and TGF beta receptor signalling." (PMID 32494274, 2020).
liver fibrosis (continued). "Plumbagin inhibits liver fibrosis by decreasing the expression of epidermal growth factor receptor (EGFR) and transcription factor 3 (STAT3) in the liver." (PMID 28770223, 2017). "The EGFR-related signal transduction pathways are activated in HSCs in liver injury and chronic liver disease to promote the development and progression of hepatic fibrosis." (PMID 27342773, 2016). "EGFR, a transmembrane receptor tyrosine kinase, has been shown to play a key role during liver fibrosis following acute and chronic liver damage." (PMID 28053995, 2016). "In brief, the current work showed that PZH may act as a therapeutic agent for liver fibrosis by inhibiting the EGFR/JAK1/STAT3 signaling axis and macrophage M1 polarization." (PMID 41181146, 2025). "While the EGFR/JAK1/STAT3 pathway is associated with fibrosis in various organs, its role in liver fibrosis remains unclear." (PMID 41181146, 2025). "Additionally, in the hepatic fibrosis mouse model, fibrotic liver tissues exhibited marked upregulation of EGFR, p-JAK1/JAK1, and p-STAT3/STAT3 protein expression (P < 0.01), accompanied by increased phosphorylation of JAK1 and STAT3 (P < 0.01)." (PMID 41181146, 2025). "•Cetuximab, an inhibitor of the EGF receptor (EGFR) prevented the liver fibrosis." (PMID 38560050, 2024). "It was also reported that EGFR may inhibit lipid accumulation and liver fibrosis through mechanisms involving the regulation of oxidative stress." (PMID 39064719, 2024). "Although we focused on the role of FUS in glomerular injury (based on our finding that FUS is expressed by mesangial cells), the finding that liver fibrosis is also mediated by nuclear FUS suggests that FUS plays a more global role in regulating fibrotic responses driven by EGFR activation." (PMID 38488009, 2024). "Recently, studies indicated that EGFR could participate in ALF, alcohol-associated liver disease, and CCl4-induced liver fibrosis." (PMID 37379130, 2023). "For example, genetic deletion of EGFR attenuated CCl4‐induced liver fibrosis." (PMID 35719043, 2022). "In addition, the MAPK and Akt signaling pathways dependent on EGFR have been revealed to be involved in pulmonary and hepatic fibrosis, among other organs fibrosis." (PMID 35224040, 2022). "More recently, PL has been reported to effectively ameliorate liver fibrosis via downregulation of epidermal growth factor receptor (EGFR), STAT3, alpha-smooth muscle actin (α-SMA), ROS-mediated NF-кB signaling pathway, and inhibition of inflammation and collagen production." (PMID 36271442, 2022). "EGFR-TKIs can promote hepatocyte proliferation, cell cycle progression in hepatocytes, and angiogenesis through a variety of mechanisms involved in induction of HSCs proliferation and activation by core targets to promote the process of liver fibrosis." (PMID 35707473, 2022). "Inhibition of EGFR leading to prevention of fibrosis in high fat diets demonstrates how EGFR could be a nexus that distinguishes asymptomatic steatosis from one that progresses into liver fibrosis." (PMID 34944593, 2021). "However, in rodent models, it was shown that EGF was downregulated in liver fibrosis, but amphiregulin and EGFR were significantly increased." (PMID 34745017, 2021). "Erlotinib, an EGFR inhibitor, could inhibit progression of liver fibrosis in DEN, BDL rat and CCl4 mouse models." (PMID 31739536, 2019). "GA could reduce the level of EGF significantly after the animal was induced with liver fibrosis; however, whether GA is an EGFR inhibitor has yet to be determined." (PMID 30627538, 2018). "EGFR is expressed on HSCs, which are thought to be the major cell type involved in liver fibrosis." (PMID 28053995, 2016). "Therefore, the current study investigated the effect of PL on liver fibrosis in a rat fibrotic liver model as well as in HSC-T6 cells and explored the possible underlying mechanisms of liver fibrosis, particularly the EGFR/STAT3 pathway." (PMID 26550019, 2015).
liver fibrosis (continued). "Moreover, the expression of several TKs, especially PDGFR, VEGFR, and EGFR, were significantly increased during the course of liver fibrosis development." (PMID 26834633, 2015). "In conclusion, plumbagin could ameliorate the development of hepatic fibrosis through its downregulation of EGFR and STAT3 in the liver, especially in hepatic stellate cells." (PMID 26550019, 2015). "All these results indicated that PL might alleviate CCl4-induced hepatic fibrosis via the EGFR/STAT3 signaling pathway." (PMID 26550019, 2015). "This activation triggers HSC transformation into myofibroblasts, inhibiting ECM degradation.Molecular docking simulations suggest that ginsenoside Rh2—a bioactive constituent of PZH—may attenuate hepatic fibrosis through modulation of the EGFR/JAK1/STAT3 signaling axis." (PMID 41181146, 2025). "The recent identification of PZH’s modulation of the EGFR/JAK1/STAT3 pathway enhances its known inhibitory effects on the TGF-β1/Smad2 axis, thereby elucidating a multifaceted mechanism against hepatic fibrosis." (PMID 41181146, 2025). "And in a murine model of hepatic fibrosis induced by CCL4, increased EGFR expression and STAT3 activation in hepatic macrophages were positively associated with M1 macrophage infiltration and collagen deposition." (PMID 41181146, 2025). "Further investigation showed that PZH ameliorates liver fibrosis by modulating key targets, including AKT1, EGFR, and STAT3." (PMID 41181146, 2025). "In our experiments, PZH administration significantly reduced the expression of EGFR, JAK1, and STAT3 in liver tissues compared to liver fibrosis mice." (PMID 41181146, 2025). "Activation of the EGFR and JAK1/STAT3 signaling pathways has been shown to promote pro-inflammatory polarization in macrophages, thereby accelerating hepatic fibrosis through mechanisms such as inflammation regulation, oxidative stress, and apoptosis." (PMID 41181146, 2025). "In line with the exacerbated liver fibrosis and elevated Bmp-1 levels, the expression of hepatocyte EMT markers, including N-cad, Vim, and EGFR was increased, while E-cad expression decreased in the livers of Periostin-deficient mice." (PMID 38216590, 2024). "Periostin-overexpressing HSCs, exhibiting a proliferative aHSC phenotype, release bone morphogenetic protein-1 (Bmp-1), which activates EGFR signaling, inducing hepatocyte EMT and contributing to liver fibrosis." (PMID 38216590, 2024). "Although these experimental results explain the effectiveness of RTK inhibition by small molecules, only two have reached clinical stage for example Erlotinib, an EGFR inhibitor and Sorafenib, a VEGFR inhibitor for improving liver fibrosis." (PMID 34944593, 2021). "Due to RECK’s inhibition of ADAM17 and consequent downregulation in EGFR signaling, it is plausible that sustaining or inducing RECK has the potential to prevent or even reverse hepatic fibrosis seen in NASH." (PMID 34745017, 2021). "Overexpression of EGFR and FGFR by activated HSC and attenuation of hepatic fibrosis by depression of those have also been demonstrated." (PMID 32148657, 2020). "Signaling through epidermal growth factor receptor (EGFR) has been shown to contribute to HSC activation and liver fibrosis." (PMID 33520984, 2020). "In the current study, Src inhibition attenuated TGF-β-induced phospho-EGFR expression in AML12 cells and primary hepatocytes; however, the effect of this inhibition on TAA-induced liver fibrosis is unclear." (PMID 32120837, 2020). "Erlotinib, EGFR kinase inhibitor, attenuated liver fibrosis and HCC development in experimental animal models by suppression of EGFR phosphorylation and inhibition of HSC activation." (PMID 27999454, 2016). "Epidermal growth factor (EGF) and its signaling molecules, EGFreceptor (EGFR) and signal transducer and activator of transcription factor 3 (STAT3), have been considered to play a role in liver fibrosis and cirrhosis." (PMID 26550019, 2015).